APP (amyloid beta precursor protein)
Diseases named in the same sentence as APP in open-access papers (continued):
Sharing a sentence is not in itself a finding about the gene and the disease.
Cognitive impairment (continued). "Nrf2 up-regulation ameliorated cognitive impairment in APP Knock-in AD mice, and in APPswe/PSEN1dE9 hypoxic mice, the intranasal administration of Nrf2 modulated CD36 protein expression, reduced Aβ deposition, and improved spatial memory." (PMID 33276671, 2020). "Senile plaque burden was lower, and these effects were accompanied by an amelioration of cognitive deficits in APP/PS1xdb/db mice." (PMID 32264944, 2020). "Since cognitive impairment is one of the major clinical characteristics of AD patients, we attempted to determine the role of CHIP in APP‐induced cognitive deficits." (PMID 31777182, 2020). "Our study revealed cognitive deficits in 2-month-old male APP/PS1 in comparison to their age-matched WT counterparts." (PMID 33384577, 2020). "Deposition of Aβ amyloid protein is a key mechanism for the development of cognitive impairment, and its main pathway is the hydrolysis of amyloid precursor protein APP into BACE1 (β-secretase 1)." (PMID 32855649, 2020). "APP/PS1 double-transgenic mice with AD imitate human progressive cognitive deficits and neuropathological characteristics, including neuroinflammation." (PMID 33059746, 2020). "The aim of the present study was to elucidate the role of GLT-1 in ceftriaxone-mediated improvement on cognitive deficits and associated changes in xCT (catalytic subunit of system xc–) expression and activity using GLT-1 knockdown APP/PS1 mice." (PMID 33132901, 2020). "Obvious cognitive deficits were observed in the AD model APP/PS1 mice in the MWM test and were associated with JNK signaling pathway activation and APP upregulation." (PMID 32116652, 2020). "First, to study the effect of LEO on cognitive impairment, 8-month-old APP/PS1 mice and WT mice were housed in individual ventilated cages (IVCs) inhaling LEO for one hour for consecutive 30 days." (PMID 32392535, 2020). "Using four different behavioral tests, we found that a one-month IG regiment of CPPs significantly attenuated cognitive impairments, decreased Aβ deposition in the APP/PS1 mice at the same time." (PMID 32652518, 2020). "Because cognitive impairment was detected in 13-month-old APP/PS1 mice, BM-MSC treatment was started at this time point." (PMID 32612165, 2020). "Here, we aimed to investigate the effects of SBP in attenuating cognitive impairment in APP/PS1 transgenic mice." (PMID 32765267, 2020). "AD can be discriminated from healthy individuals considering the ratio of pTau-T181/total Tau, and from mild cognitive impairment considering the pTau-T181/total Tau ratio and the APP levels in plasma-derived EVs." (PMID 33362690, 2020). "After rTMS treatment, the AD‐like cognitive impairments of APP/PS1 mice were investigated subsequently, and molecular mechanisms underlying was further explored." (PMID 32592331, 2020). "The study showed that the two‐week rTMS at 5Hz frequency improved cognitive impairments and AD‐like pathology of APP/PS1 mice via autophagy." (PMID 32592331, 2020). "Recently, we revealed that dihydrokainic acid inhibited the improvement of Cef on cognitive impairment in APP/PS1 mice." (PMID 33132901, 2020). "Most recently, we observed that injection of δ-secretase into the brain of human wild-type APP/Tau double transgenic mice evidently accelerates enormous senile plaques and NFT in both sexes, associated with prominent synaptic defects and cognitive deficits." (PMID 32859953, 2020). "Consistent with findings reported here, cognitive impairment was spared with reduced levels of Aβ trimers in the hippocampus of APP/PSS1 mouse, another AD model." (PMID 33238473, 2020). "It was found that one-month intragastric administration of CPPs significantly ameliorated cognitive defects in APP/PS1 mice." (PMID 32652518, 2020). "Here we report that depletion of CHIP effectively palliated APP‐induced pathological symptoms, including morphological, behavioral, and cognitive defects." (PMID 31777182, 2020).
Cognitive impairment (continued). "APP/PS1 transgenic mouse is one the most popular animal models to mimic the cognitive impairment of AD patients." (PMID 32765267, 2020). "The findings provide convincing evidence for the conclusion that Cef improves cognitive impairment of APP/PS1 AD mice by upregulating GLT-1 expression and uptake activity." (PMID 33132901, 2020). "In the Morris water maze test, the APP/PS1 mice showed severe cognitive impairment compared with the WT mice." (PMID 32724479, 2020). "In the present study, the data showed that 27-OHC effectively aggravated cognitive deficits in the APP/PS1 mice as shown by the Morris water maze test and the passive avoidance test." (PMID 32593306, 2020). "The AD‐like cognitive impairments and AD‐related neuropathological features of APP/PS1 mice were investigated subsequently after rTMS treatment, and molecular mechanisms underlying was further explored." (PMID 32592331, 2020). "Next, the effects of BACE1 inhibitor infusion were examined in a mouse model overexpressing human APP, the hAPP23 mouse, which has higher expression of APP than hAPPSw, and exhibits early cognitive impairment and extensive Aβ pathology (at 3–6 months)." (PMID 32407295, 2020). "In conclusion, we have provided new experimental evidence for a critical role of 27-OHC in gut dysbiosis and impairment of intestinal barrier permeability that aggravates inflammation and leads to cognitive deficits and an increased Aβ load in APP/PS1 mice." (PMID 32593306, 2020). "Alterations in CNTN4 expression have been implicated to negatively affect the proteolytic processing of APP, which contributes to impairments in axon guidance and synaptic plasticity, reduced neuronal survival, and ultimately results in cognitive impairments." (PMID 33519384, 2020). "In this study, we found that blocking autophagy not only reduces Aβ production and accumulation, but also suppresses APP‐induced morphological, behavioral, and cognitive defects." (PMID 31777182, 2020). "It is found in some researches that miR-101 expression is reduced in the cognitive disorder-affected brain cortex, which leads to the increased APP expression and elevated production of Aβ lesion." (PMID 32855649, 2020). "In the current study, we found that CPPs significantly ameliorated cognitive defects in APP/PS1 mice after one-month intragastric administration." (PMID 32652518, 2020). "Consistent with the results of APP/PS1 mouse model, all these findings suggest that p47phox deficiency improves cognitive impairment in AD." (PMID 33183342, 2020). "mTOR inhibitor rapamycin activates autophagy, alleviates the accumulation of Aβ and ameliorates cognitive deficits in mice expressing mutant APP." (PMID 32457595, 2020). "Our findings demonstrate that early preventive IIV immunization activates the immune system, enhances the microglial response to plaques, rebalances the disordered cerebral immune milieu and ultimately alleviates cognitive deficits in APP/PS1 mice." (PMID 32075657, 2020). "Compared with the WT mice, the APP/PS1 mice exhibited a severe cognitive impairment, but IIV significantly improved such deficits." (PMID 32075657, 2020). "In the present study, we confirmed the upregulation of GLT-1 expression and improvement on cognitive impairments after treatment of Cef in APP/PS1 AD mice." (PMID 33132901, 2020). "Our results here indicate that SNX8 levels are attenuated in human AD and mouse APP/PS1 AD models; SNX8 mediates APP trafficking from amyloidogenic endosomal compartments, and suppresses Aβ generation and cognitive impairment in APP/PS1 mice." (PMID 31551717, 2019). "Tolfenamic acid can attenuate cognitive deficits in APP transgenic mice after 2 weeks of administration." (PMID 31049134, 2019). "It is very well documented that APP/PS1 mice develop cognitive deficits by 7 months of age, which are clearly pronounced at the age of 18 months." (PMID 30003517, 2019).
Cognitive impairment (continued). "The earliest signs of cognitive impairments in APP/PS1 mice have been reported in six-month-old animals." (PMID 31510042, 2019). "Altogether, these behavioral tests show that miR-181a overexpression in the brain ameliorates cognitive deficits in APP/PS1 mice, including impaired spatial learning and memory." (PMID 31467256, 2019). "We demonstrated that UA ameliorated cognitive impairment, prevented neuronal apoptosis, and enhanced neurogenesis in APP/PS1 mice." (PMID 30871577, 2019). "Accelerated cognitive decline has been reported in AQP4 deficient APP/PS1 mice and intraneuronal Aβ deposits are associated with neuron loss and cognitive deficit." (PMID 31068220, 2019). "In this study, we observed that EA intervention on AD mice reduced BACE1 through downregulating APP cleavage to ameliorate cognitive impairments." (PMID 31223308, 2019). "On the other hand, APP-overexpressing models show more variability with respect to the onset of cognitive deficits in relation to pathology." (PMID 31705038, 2019). "In line with this, our results showed that treatment of YU102 not only improves cognitive deficits but also blocks RPE degeneration triggered by Aβ-induced inflammation in the APP transgenic mouse model." (PMID 31804556, 2019). "As a key player in the cognitive impairment of AD, Aβ is produced by sequential enzymatic cleavage of amyloid precursor protein (APP) by β- and γ-secretases." (PMID 31632239, 2019). "Consistent with other AD animal models, we have previously reported that voluntary wheel running exercise improved cognitive deficits and attenuated Aβ deposits in APP/PS1 AD animal model." (PMID 31024293, 2019). "Compared to age-matched WT mice, young, adult and middle-aged tPA-/- mice exhibit significant cognitive impairment, axonal damage, and increased deposition of amyloid precursor protein (APP), Aβ, and fibrin." (PMID 31440383, 2019). "Consistently, DISC1 shows decreased levels in the brains of 8‐month‐old APP/PS1 transgenic mice, which exhibit AD‐like symptoms such as cognitive deficits, accumulation of Aβ, and loss of synapses." (PMID 30488644, 2019). "Previous reports have shown cognitive impairment as a late occurrence of the APP/PS1 mice in the Morris water maze starting from 7 to 8 months." (PMID 31592131, 2019). "An APP/PS1 mouse model develops reference memory cognitive impairments at a later age (and at a temporally slower pace) than the 5xFAD model." (PMID 30934587, 2019). "Taken together, these results suggest that L41 treatment alleviates synaptic plasticity impairments and rescues memories defects in aged APP/PS1 mice (14-month-old) with well-established cognitive deficits." (PMID 30885273, 2019). "Our results demonstrated for the first time that MSL treatment prevented the progression to cognitive deficits in APP/PS1 mice in the early stages of AD." (PMID 29636677, 2018). "Next to cognitive deficits, APP/PS1 mice have been described to exhibit reduced AHN around the age of 9–10 months, although there are expectations as well." (PMID 29563870, 2018). "Several studies demonstrated that hyperinsulinemia and insulin resistance triggers cognitive impairment and Aβ and amyloid precursor protein (APP) deposition." (PMID 30469430, 2018). "The authors found that the elimination of Tregs boosted the onset of signs of cognitive impairment in APPPS1 mice (mice in which the expression of human APP transgene is approximately 3-fold higher than in endogenous murine APP)." (PMID 29755324, 2018). "Our results indicated that at an early stage, MSL treatment ameliorated cognitive impairment and neurodegeneration in APP/PS1 mice." (PMID 29636677, 2018). "This is the earliest recorded behavioral deficit; earlier reports have shown impaired LTP at 3 months and APP/PS1 mice show cognitive deficits in the contextual memory and its extinction at 4–6 months of age." (PMID 29246925, 2018).
Cognitive impairment (continued). "The facts of cognitive impairment in animals with epileptiform activity were derived from different studies devoted to the role of the tau peptide or APP overexpression in mouse models of AD." (PMID 30210311, 2018). "Synaptic deficits correlate closely to cognitive impairment in AD and TNFα inhibitors have been shown to rescue cognitive impairments in APP mouse models." (PMID 30135948, 2018). "In summary, all these data suggest that metformin inhibits the MID1-dependent translation of APP and thereby reduces Aβ plaque burden and improves cognitive impairments in an AD mouse model." (PMID 29531801, 2018). "In the meantime, scutellarin mitigates amyloid pathology and related cognitive deficits after nine months of treatment in APP/PS1 transgenic mice." (PMID 29642616, 2018). "Intracerebroventricular administration of APP96-110 was shown to not only restore motor and cognitive deficits, but also preserve cortical and hippocampal tissue in APP-/- mice, and reduce axonal injury in the corpus callosum following diffuse TBI in rats." (PMID 29320530, 2018). "Although APP/PS1 transgenic mice display obvious cognitive impairments by 12 months of age, at 6 months of age their performance is comparable to that of wild-type mice in the hippocampal-dependent spatial learning task, the Morris water maze." (PMID 29520217, 2018). "After nine months of treatment, we evaluated the preventive effects of scutellarin on cognitive deficits in APP/PS1 mice." (PMID 29642616, 2018). "A third cohort of mice of all four experimental groups (cohort 3) was aged until 8 months with the aim to test if ES would have aggravated cognitive deficits in APP/PS1 mice." (PMID 29563870, 2018). "The APPswe/PS1dE9 (APP/PS1) mouse model has been widely used to study cognitive deficits related to AD." (PMID 30079347, 2018). "Even so, severe cognitive impairment was still observed in APP/PS1 mice, as suggested by notably slower improvement in escape latency in Tg-PBS group." (PMID 29061973, 2017). "APP/PS1 mice had typical cognitive impairment, embodied in the longer swimming distance to platform, longer time to platform, shorter time in target quadrant, and fewer times of crossing the original platform." (PMID 28931427, 2017). "Based on previous results, cognitive impairments in APP/PS1 mice over 6 months old were observed in the MWM and passive avoidance behavior tasks." (PMID 28358909, 2017). "Our data demonstrate for the first time that LIG is able to reduce cerebral Aβ burden and improve cognitive impairment in the APP/PS1 transgenic mouse model of AD via enhancing ADAM10 activity." (PMID 29163135, 2017). "Compared with the behavioral data on Tg2576 APPswe mice, the present data provides evidence of an accelerator role of PS2 on cognitive impairments in APP transgenic mice." (PMID 29333315, 2017). "For example, we previously demonstrated that activation of ADRB1 reverses AD-like cognitive deficits in transgenic mice overexpressing human amyloid beta protein precursor (APP)." (PMID 28746336, 2017). "Collectively, results indicated that 5-HT6 antagonist SB271046 recovered the cognitive impairment of APP/PS1 mice." (PMID 28931427, 2017). "In conclusion, the present findings show that LXR agonist treatment of Abca1 haplo-deficient APP/E4 mice, ameliorates APOE4 driven brain pathology and cognitive deficits." (PMID 28241068, 2017). "In this study, we attempted to investigate the effects of ICS II, on cognitive deficits and beta-amyloid (Aβ) production in APPswe/PS1dE9 (APP/PS1) double transgenic mice." (PMID 28337142, 2017). "Of note, cognitive impairment that has been described in numerous APP transgenic models has been more variable in knock-in models, albeit far less well studied." (PMID 29273078, 2017). "In this study, we examined the effect of LIG on cognitive impairment in the APP/PS1 double-transgenic mouse model of AD." (PMID 29163135, 2017).
Cognitive impairment (continued). "BACE1 is not only a dominant enzyme in Aβ synthesis from APP but also functions as an aspartic protease with altered enzymatic activity and protein expression in the brain early in the development of mild cognitive impairment." (PMID 28851397, 2017). "This mouse model expresses mutant human amyloid precursor protein (APP) and presenilin protein 1 (PS1), causing AD‐like amyloid plaque formation as early as 4 months of age while cognitive impairment becomes observable around 6–8 months of age." (PMID 27861127, 2017). "The results of the contextual fear conditioning test presented in the current study demonstrate an age-dependent cognitive impairment in a double-transgenic APP/PS2 mouse model of AD." (PMID 29333315, 2017). "Here we showed that BJJS treatment alleviated cognitive impairment in APP/PS1 mice via evaluating the learning and memory abilities by the Morris water maze and novel object recognition tests." (PMID 29190943, 2017). "In this study, we firstly demonstrated that YXQN reduced AD-like pathology and cognitive impairment in APPswePS1dE9 (APP/PS1) mice with 2 months administration." (PMID 28603494, 2017). "In APP-/- mice, APP96-110 was able to restore motor and cognitive deficits, associated with greater preservation of cortical and hippocampal tissue, so that they were no longer significantly different to APP wildtypes." (PMID 27114849, 2016). "LW-AFC ameliorated the cognitive impairment observed in APP/PS1 mice, including the impairment of object recognition memory, spatial learning and memory, and active and passive avoidance." (PMID 27964740, 2016). "The odor recognition task has proven to be sensitive to age-dependent cognitive impairment in APP/PS1 mice." (PMID 27014054, 2016). "In this study, we evaluated the therapeutic effect of Bacopaside I (BS-I), a major triterpenoid saponin of BME, on the cognitive impairment and neuropathology in APP/PS1 transgenic mice and explored the possible mechanism from a biological systems perspective." (PMID 26946062, 2016). "In order to obtain the NIM network underlying cognitive impairment, we submitted the factors significantly correlated with cognition of SAMP8 mice and APP/PS1 mice, obtained by multiple linear regression analysis, to MetaCore database, respectively." (PMID 27049828, 2016). "To identify the differences and similarities between NIM network underlying cognitive impairment of SAMP8 and APP/PS1 mice, we adapted the “network fingerprint” frameworks introduced by our colleagues recently." (PMID 27049828, 2016). "APP-/- mice demonstrated greater motor and cognitive deficits, increased vulnerability of neurons to injury and a defective reparative response to injury, compared to wildtype mice." (PMID 27114849, 2016). "The data from our study represent the first evidence to support that the prolonged administration of BS-I can ameliorate the age-related cognitive impairments and Aβ accumulation observed in APP/PS1 mice." (PMID 26946062, 2016). "In conclusion, our study demonstrate that BS-I can reduce the Aβ level in the brains of AD mice, protect neurons from injury, improve the activity of anti-oxidative enzymes and ameliorate cognitive impairment in the APP/PS1 mouse model." (PMID 26946062, 2016). "On above all, the present study provided a new insight into the mechanisms underlying cognitive impairments in SAMP8 and APP/PS1 mice." (PMID 27049828, 2016). "In this study, we report for the first time that the chronic administration of BS-I reduces Aβ deposits and ameliorates cognitive impairments in a well-established strain of APP/PS1 transgenic mice." (PMID 26946062, 2016). "Neural stem cell implantation in the triple transgenic AD mice (3xTg-AD) that harbor mutated human APP, tau, and PS1, has been reported to rescue cognitive impairment via increased brain derived neurotrophic factor (BDNF) expression." (PMID 27400746, 2016).